CLCN6 (Cl-/H+ antiporter 6)
Description:
Voltage-gated channel mediating the exchange of chloride ions against protons. Functions as antiporter and contributes to the acidification of the late endosome lumen. The CLC channel family contains both chloride channels and proton-coupled anion transporters that exchange chloride or another anion for protons. The presence of conserved gating glutamate residues is typical for family members that function as antiporters.
Synonyms: ClC-6; KIAA0046; CONRIBA
Tractability: Small molecule: a structure with a bound ligand is known. Antibody: UniProt predicts a signal peptide or a membrane-spanning region. PROTAC: ubiquitination databases record sites on it; its protein half-life has been measured.
Gene: Protein-coding gene on chromosome 1 (11,806,096 to 11,848,079, forward strand). Ensembl gene ENSG00000011021.
Subcellular location: Late endosome membrane
Subcellular location (Human Protein Atlas): Cytosol; Plasma membrane
Pathways (Reactome):
Disease: Signaling by BRAF and RAF1 fusions
Transport of small molecules: Stimuli-sensing channels
Gene Ontology:
Molecular function: voltage-gated chloride channel activity; antiporter activity; chloride channel activity; chloride transmembrane transporter activity
Biological process: chloride transport; cell volume homeostasis; monoatomic ion transmembrane transport; signal transduction; chloride transmembrane transport; response to mechanical stimulus; transmembrane transport
Cellular component: late endosome membrane; lysosomal membrane; endosome membrane; late endosome; membrane
Genetic constraint (gnomAD): Loss-of-function variants: 66 observed, 102.95 expected, observed/expected ratio (o/e) 0.64, 90% interval 0.52 to 0.79. The upper end of that interval is the gene's LOEUF score, 0.79, which puts it in group 3 of 6, group 1 being the genes least tolerant of losing a copy. Missense variants: 938 observed, 1,123 expected, observed/expected ratio (o/e) 0.84, 90% interval 0.79 to 0.88. Synonymous variants: 424 observed, 445.22 expected, observed/expected ratio (o/e) 0.95, 90% interval 0.88 to 1.03.
Homologues: Orthologues: macaque CLCN6 (99% identical), guinea pig CLCN6 (98% identical), dog CLCN6 (98% identical), chimpanzee CLCN6 (97% identical), pig CLCN6 (97% identical), mouse Clcn6 (97% identical), rabbit CLCN6 (95% identical), rat Clcn6 (93% identical), tropical clawed frog clcn6 (87% identical), zebrafish clcn6 (83% identical), Drosophila melanogaster ClC-c (24% identical), Caenorhabditis elegans clh-5 (24% identical). Paralogues in human: CLCN7 (39% identical), CLCN5 (25% identical), CLCN3 (25% identical), CLCN4 (25% identical), CLCN2 (21% identical), CLCN1 (19% identical), CLCNKB (17% identical), CLCNKA (17% identical).
Diseases named in the same sentence as CLCN6 in open-access papers:
CLCN6 is named in the same sentence as 42 diseases in open-access papers, as found by Europe PMC text mining. Sharing a sentence is not in itself a finding about the gene and the disease. The quoted sentences say what the papers report.
neuronal ceroid lipofuscinosis (7 papers, 2015 to 2025). "More recently, mutations in ClCN6 have been identified as a new genetic cause of neuronal ceroid lipofuscinosis (NCL), a group of serious neurodegenerative disorders from lysosomial accumulation." (PMID 41010403, 2025). "Clcn6−/− knockout mice showed mild neuronal lysosomal storage disease, resembling the phenotype observed in two patients carrying ClC-6 heterozygous missense mutations (V580M and T628R) and affected by neuronal ceroid lipofuscinosis (NCL)." (PMID 38027030, 2023). "Worth noting is that while SNPs in CLCN6 are associated with lower DP, they have also been found to be associated with seizure and epilepsy in some populations, and a Clcn6 deficient mouse had characteristics of mild neuronal ceroid lipofuscinosis, a lysosomal storage disease." (PMID 35927940, 2022). "ClC-6 KO (Clcn6−/−) mice display reduced pain sensitivity and mild nonspecific cognitive abnormalities resembling mild forms of human neuronal ceroid lipofuscinosis (NCL)." (PMID 37831762, 2023). "Knock-out of CLCN6 in mice did not result in increased lethality or produce a strong phenotype, but moderate neuronal pathology, resembling that in mild forms of human neuronal ceroid lipofuscinosis (NCL), has been observed." (PMID 25794116, 2015).
Hypertension (6 papers, 2020 to 2025). The presence of chronic increased pressure in the systemic arterial system. "The study identified rare loss-of-function and missense variants in CLCN6, a chloride channel gene, which were associated with lower diastolic BP (−3.3 mmHg) and a 28% reduction in hypertension risk (OR = 0.72)." (PMID 41573461, 2025). "The role of CLCN6 in blood pressure regulation is known as discussed, GWAS and sequencing studies have linked mutations and variants within this gene to hypertension." (PMID 37754271, 2023). "Many rare coding mutations and intronic single nucleotide polymorphisms in CLCN6 have been related with decreased blood pressure and hypertension, along with stroke risk as based on recent GWAS findings in humans." (PMID 36320003, 2022). "The outcome of the MR analysis was also consistent; namely, higher methylation at the cg05228408 site was associated with higher levels of CLCN6 (B = 0.81, p = 3.0 × 10−42), and consequently, this was associated with a lower risk of hypertension (B = −0.02, p = 2.4 × 10−18)." (PMID 37754271, 2023). "In this way these authors could show that several genes impact hypertension and that multiple causative gene variants cosegregate at this locus; several linked genes thus control blood pressure (Agtrap, Clcn6, Mthfr, Nppa, Plod1)." (PMID 32741357, 2020). "Sequencing-based evidence thus enhances the foundation for precision hypertension management, enabling gene-based risk stratification and therapeutic targeting of molecular pathways like KCNK3, ENPEP, and CLCN6." (PMID 41573461, 2025). "I found mQTLs for cg05228408, and eQTLs for CLCN6 showed overlap with the GWAS signal for hypertension." (PMID 37754271, 2023). "By integrating the eQTL data, I noted GWAS signals for hypertension and cg05228408 overlap with eQTLs for CLCN6." (PMID 37754271, 2023). "CLCN6 is a voltage-dependent chloride channel and has a role in regulating blood pressure levels and hypertension." (PMID 35326596, 2022). "We found that loss of function mutation in Clcn6 on the Dahl SS rat background does not convey protection against hypertension‐induced stroke mortality, potentially due to confounding altered expression of Mthfr, Nppa, and Nppb." (PMID 35927940, 2022).
epilepsy (5 papers, 2017 to 2025). A brain disorder characterized by episodes of abnormally increased neuronal discharge resulting in transient episodes of sensory or motor neurological dysfunction, or psychic dysfunction. "Currently, mutations in the CLCN1, CLCN2, CLCN3, CLCN4, and CLCN6 genes have been reported to be associated with various forms of epilepsy." (PMID 40223930, 2025). "In this regard, the authors find that interactions of circEFCAB2 with miR-485-5p and circ-DROSHA with miR-1252-5p were highly correlated with the expression of epilepsy-associated genes CLCN6 and ATP1A2, respectively." (PMID 35328484, 2022). "This highlights the complexity of the genetic contributions to epilepsy and the need for more research to fully elucidate the role of CLCN6 in neurological disorders." (PMID 40223930, 2025). "Overall, these studies suggest a potential association between the CLCN6 gene and epilepsy; however, observations from ClCN6 knockout mice indicate that these animals do not exhibit epilepsy or severe neurological defects." (PMID 40223930, 2025). "Among the top ten hyper- and top ten hypo-methylated genes, a subset (i.e., GABRB1, LC34A2, CLCN6, CLCA4, CYP3A43, CYP3A4, CYP2C9) has been related to epilepsy in epidemiological, pathophysiological or clinical context (to be discussed further)." (PMID 28276448, 2017).
Stroke (4 papers, 2020 to 2023). Sudden impairment of blood flow to a part of the brain due to occlusion or rupture of an artery to the brain. "In attempting to understand the role of CLCN6 in stroke, we have additionally discovered that a mutation in this conserved region is associated with altered expression of nearby blood pressure homeostasis genes." (PMID 35927940, 2022). "Additionally, a recent study found sickle cell anemia patients with mutations in CLCN6 had improved survival and reduced stroke risk." (PMID 35927940, 2022). "Genetic variants, such as those in CLCN6 that reduce BP may also be expected to lower the risk of stroke within this population." (PMID 35927940, 2022). "Additionally, the AGTRAP‐PLOD1 locus gene cluster where CLCN6 is localized has been associated with stroke along with other BP regulatory genes such as MTHFR, NPPA, and NPPB." (PMID 35927940, 2022). "Given that increased blood pressure is a major risk factor for stroke in SCD, the result suggests that SCD patients with some specific variants in CLCN6 live longer due to a reduced risk of stroke." (PMID 36815490, 2023). "Conversely, five genes (CLCN6, OGDHL, COL6A3 [MIM: 120250], INSR [MIM: 147670], and NOS3 [MIM: 163729]) were found in the “long survivor” group but not in the “stroke” group." (PMID 32898326, 2020).
West syndrome (4 papers, 2017 to 2025). "A missense mutation of CLCN6 has been seen in a single patient with the early infantile epileptic encephalopathy West syndrome, and this sequence change causes autophagosome accumulation and blockage of autophagosome-lysosome fusion." (PMID 35140266, 2022).
developmental delay (2 papers, 2022 to 2023). "Mutations in Clcn6 in mice lead to mild lysosomal storage abnormalities, whereas in humans, a CLCN6 mutation causes a severe developmental delay with pronounced neurological and neurodegenerative problems." (PMID 36830826, 2023).
keratinocyte carcinoma (2 papers, 2022). A skin cancer arising from the keratin-producing cells of the epidermis. "This study of a combined renal transplant population illustrates an increased hazard ratio of 1.5 of keratinocyte cancer, with the CT or TT variant of Chloride transport protein 6 (CLCN6) rs9651118." (PMID 35677930, 2022). "Polymorphism at methylenetetrahydrofolate reductase CLCN6 was closely related to keratinocyte cancer in renal transplant recipients." (PMID 36246902, 2022). "In conclusion we present a SNP in the CLCN6 MTHFR overlap gene associated with an increased risk of keratinocyte cancer in RTRs." (PMID 35677930, 2022).
psoriasis (2 papers, 2022 to 2023). An autoimmune condition characterized by red, well-delineated plaques with silvery scales that are usually on the extensor surfaces and scalp. "Some psoriasis loci showed a substantial single-tissue eQTL, primarily in the cardiovascular system (artery coronary: rs240993/KIAA1919, rs9808753/TMEM50B, heart left ventricle: rs11053802/KLRC4, heart left ventricle: rs11053802/KLRK1, rs5063/CLCN6, rs1050414/HLA-B, rs2778031/SPIN1)." (PMID 36320003, 2022).
Respiratory insufficiency (2 papers, 2022). "Heterozygous mutation of CLCN6 is associated with a rare neurological disorder that exhibits childhood-onset neurodegeneration with hypotonia, respiratory insufficiency, and brain imaging abnormalities." (PMID 35140266, 2022).
asthma (1 paper, 2020). "The combined interaction scores resulted in higher interactions for the genes STAT3, AGO2, COL1A1, CLCN6, and KSR for moderate asthma and JAK2, INSR, ERBB2, NR3C1, and PTK6 for severe asthma." (PMID 32512817, 2020). "For example, in severe asthma, the combined interaction scores for the STAT3, AGO2, COL1A1, CLCN6, and KSR1 genes yielded a higher interaction for the moderate asthma phenotype, and the JAK2, INSR, ERBB2, NR3C1, and PTK6 genes were more interactive for the severe asthma phenotype." (PMID 32512817, 2020).
gastroenteritis (1 paper, 2015). An inflammatory disorder that affects the upper and lower gastrointestinal tract. "Next, we performed a cohort study for CLCN6 in 48 BPEI patients without PRRT2 mutations and six patients who had convulsions associated with mild gastroenteritis." (PMID 25794116, 2015).
neural tube defect (1 paper, 2020). A congenital defect characterized by failure of the neural tube to close completely; this results in the presence of openings in the brain or spinal cord. "Moreover, chloride voltage-gated channel 6 (CLCN6) was found to be involved in lung vasodilatation, pulmonary permeability, and bronchorelaxation and is correlated with disorders, including neural tube defects, folate sensitivity, and benign childhood epilepsy." (PMID 32512817, 2020).
pilocytic astrocytoma (1 paper, 2020). Pilocytic astrocytoma is a rare subtype of low-grade glioma of the central nervous system characterized by a well circumscribed, often cystic, brain tumor with a discrete mural nodule and long, hair-like projections that extend from the neoplastic astrocytes. "It is nevertheless important to note that the presented BRAF multiplexed assay is not designed to detect other rare fusions involving BRAF that have been reported in pilocytic astrocytomas including FAM131:BRAF, RNF130:BRAF, CLCN6:BRAF, MKRN1:BRAF, GNAI1:BRAF, and GTF2I:BRAF." (PMID 33282733, 2020).
sickle cell anemia (1 paper, 2022). "A recent paper found that loss of function mutations in CLCN6 were associated with a “long survivor” group of Cameroonian sickle cell anemia patients." (PMID 35927940, 2022). "Additionally, if this crosstalk between the genes is similar in humans, it may in part explain how the loss of function mutations in CLCN6 are associated with the “long survivor” sickle cell anemia patient cohort." (PMID 35927940, 2022).
cancer (1 paper, 2022). A tumor composed of atypical neoplastic, often pleomorphic cells that invade other tissues. "Studies have revealed that CLCN2 and CLCN6 could participate in the regulation of various energy metabolism and other cancer biology." (PMID 36246902, 2022). "Enrichment analysis on cancer-related pathways and processes correlated to our signature indicated that alteration of CLCN2 or CLCN6 expression could affect cell volume based on biological regulation and assembly of genetic material." (PMID 36246902, 2022).
CLCN6 also shares sentences with these, for which no sentence is quoted: lysosomal storage disease (5 papers); neurological disorder (3); Myotonia (2); Arrhythmia (1); benign familial infantile epilepsy (1); breast carcinoma (1); cardiomyopathy (1); cardiovascular disease (1); Cerebral atrophy (1); Cognitive impairment (1); COVID-19 (1); dementia (1); Epileptic encephalopathy (1); genetic diseases (1); gestational hypertension (1); glioblastoma (1); glioma (1); hyperaldosteronism (1); kidney diseases (1); neuroblastoma (1); Neurodevelopmental delay (1); Neurogenic bladder (1); neuropathies (1); osteopetrosis (1); primary progressive aphasia (1); skin cancer (1); tumor (1).